GRIA1 (glutamate ionotropic receptor AMPA type subunit 1)
Description:
Ionotropic glutamate receptor that functions as a ligand-gated cation channel, gated by L-glutamate and glutamatergic agonists such as alpha-amino-3-hydroxy-5-methyl-4-isoxazolepropionic acid (AMPA), quisqualic acid, and kainic acid. L-glutamate acts as an excitatory neurotransmitter at many synapses in the central nervous system. Binding of the excitatory neurotransmitter L-glutamate induces a conformation change, leading to the opening of the cation channel, and thereby converts the chemical signal to an electrical impulse upon entry of monovalent and divalent cations such as sodium and calcium. The receptor then desensitizes rapidly and enters in a transient inactive state, characterized by the presence of bound agonist (By similarity). In the presence of CACNG2 or CACNG4 or CACNG7 or CACNG8, shows resensitization which is characterized by a delayed accumulation of current flux upon continued application of L-glutamate. Resensitization is blocked by CNIH2 through interaction with CACNG8 in the CACNG8-containing AMPA receptors complex. Calcium (Ca(2+)) permeability depends on subunits composition and, heteromeric channels containing edited GRIA2 subunit are calcium-impermeable. Also permeable to other divalents cations such as strontium(2+) and magnesium(2+) and monovalent cations such as potassium(1+) and lithium(1+) (By similarity).
Synonyms: GLUA1; GLUH1; GLUR1; GLURA; HBGR1; MRD67; MRT76
Tractability: Small molecule: an approved drug acts on it; a high-quality ligand is known; it belongs to a druggable protein family. Antibody: UniProt places it where antibodies can reach, with high confidence; its Gene Ontology location is reachable by antibodies, with high confidence; UniProt predicts a signal peptide or a membrane-spanning region. PROTAC: ubiquitination databases record sites on it; its protein half-life has been measured; a small molecule that binds it is known.
Target class: Ligand-gated ion channel; Ionotropic glutamate receptor; AMPA receptor; Ion channel
Gene: Protein-coding gene on chromosome 5 (153,489,615 to 153,813,869, forward strand). Ensembl gene ENSG00000155511.
Subcellular location: Cell membrane; Endoplasmic reticulum membrane; Postsynaptic cell membrane; Postsynaptic density membrane; Cell projection, dendrite; Cell projection, dendritic spine; Early endosome membrane; Recycling endosome membrane; Presynapse; Synapse
Pathways (Reactome):
Neuronal System: Activation of AMPA receptors; Long-term potentiation; Synaptic adhesion-like molecules; Trafficking of AMPA receptors; Trafficking of GluR2-containing AMPA receptors; Unblocking of NMDA receptors, glutamate binding and activation
Vesicle-mediated transport: COPII-mediated vesicle transport; Cargo concentration in the ER
Gene Ontology:
Molecular function: AMPA glutamate receptor activity; ligand-gated monoatomic ion channel activity involved in regulation of presynaptic membrane potential; protein binding; amyloid-beta binding; glutamate-gated calcium ion channel activity; PDZ domain binding; transmitter-gated monoatomic ion channel activity involved in regulation of postsynaptic membrane potential; adenylate cyclase binding; beta-2 adrenergic receptor binding; G-protein alpha-subunit binding; G-protein beta-subunit binding; glutamate receptor binding; glutamate-gated receptor activity; identical protein binding; immunoglobulin binding; ligand-gated calcium channel activity; ligand-gated monoatomic ion channel activity; monoatomic ion channel activity; myosin V binding; peptide hormone receptor binding; protein domain specific binding; protein kinase A binding; protein kinase binding; scaffold protein binding; signaling receptor activity; and 1 more
Biological process: chemical synaptic transmission; ionotropic glutamate receptor signaling pathway; modulation of chemical synaptic transmission; signal transduction; synapse assembly; synaptic transmission, glutamatergic; behavioral response to pain; calcium-mediated signaling; cellular response to amine stimulus; cellular response to amino acid stimulus; cellular response to brain-derived neurotrophic factor stimulus; cellular response to dsRNA; cellular response to glycine; cellular response to growth factor stimulus; cellular response to L-glutamate; cellular response to peptide hormone stimulus; cerebral cortex development; conditioned place preference; long-term memory; long-term synaptic potentiation; monoatomic ion transmembrane transport; monoatomic ion transport; neuronal action potential; positive regulation of excitatory postsynaptic potential; positive regulation of gene expression; and 24 more
Cellular component: AMPA glutamate receptor complex; dendritic spine membrane; plasma membrane; postsynaptic membrane; recycling endosome; cell surface; dendrite; dendritic spine; early endosome membrane; endocytic vesicle membrane; endoplasmic reticulum membrane; endoplasmic reticulum-Golgi intermediate compartment membrane; ER to Golgi transport vesicle membrane; neuron spine; neuronal cell body; postsynaptic density; postsynaptic density membrane; presynapse; recycling endosome membrane; Schaffer collateral - CA1 synapse; synapse; synaptic membrane; asymmetric synapse; cell-cell junction; cytosol; and 15 more
Genetic constraint (gnomAD): Loss-of-function variants: 28 observed, 85.76 expected, observed/expected ratio (o/e) 0.33, 90% interval 0.24 to 0.45. The upper end of that interval is the gene's LOEUF score, 0.45, which puts it in group 1 of 6, group 1 being the genes least tolerant of losing a copy. Missense variants: 718 observed, 1,117.3 expected, observed/expected ratio (o/e) 0.64, 90% interval 0.6 to 0.68. Synonymous variants: 412 observed, 417.08 expected, observed/expected ratio (o/e) 0.99, 90% interval 0.91 to 1.07.
Gene-disease validity (ClinGen):
ClinGen rates the evidence that GRIA1 causes each of these diseases.
complex neurodevelopmental disorder (autosomal dominant): Moderate. A disorder that involves more than one phenotype associated with the central nervous system, including but not limited to intellectual disability, autism, and seizures (epilepsy).
complex neurodevelopmental disorder (autosomal recessive): Limited.
Homologues: Orthologues: dog GRIA1 (99% identical), pig GRIA1 (99% identical), rat Gria1 (99% identical), mouse Gria1 (98% identical), macaque GRIA1 (98% identical), chimpanzee GRIA1 (97% identical), rabbit GRIA1 (96% identical), guinea pig GRIA1 (94% identical), tropical clawed frog gria1 (89% identical), zebrafish gria1a (76% identical), zebrafish gria1b (74% identical), Drosophila melanogaster GluRIB (44% identical), and 38 more. Paralogues in human: GRIA2 (68% identical), GRIA4 (67% identical), GRIA3 (66% identical), GRIK2 (38% identical), GRIK1 (38% identical), GRIK3 (37% identical), GRIK4 (34% identical), GRIK5 (34% identical), GRID1 (28% identical), GRIN1 (25% identical), GRID2 (25% identical), GRIN2C (22% identical), and 5 more.
Diseases named in the same sentence as GRIA1 in open-access papers:
GRIA1 is named in the same sentence as 152 diseases in open-access papers, as found by Europe PMC text mining. Sharing a sentence is not in itself a finding about the gene and the disease. The quoted sentences say what the papers report.
schizophrenia (68 papers, 2008 to 2025). A major psychotic disorder characterized by abnormalities in the perception or expression of reality. "The GluA1 subunit, encoded by the putative schizophrenia-associated gene GRIA1, is required for activity-regulated AMPA receptor (AMPAR) trafficking, and plays a key role in cognitive and affective function." (PMID 41275019, 2025). "An additional rationale for choosing this model was that recent genome-wide association studies have linked the GRIA1 gene, which encodes GluA1, with schizophrenia, and in line with this, GRIA1−/− mice show phenotypes relevant for schizophrenia." (PMID 39241075, 2024). "For example, a genome-wide significant association to schizophrenia has been established for the Gria1 locus which codes for the GluA1 subunit of the AMPA glutamate receptor." (PMID 36460723, 2023). "An earlier study in the Italian population revealed an association of GRIA1 rs1422884 with schizophrenia susceptibility." (PMID 37964012, 2023). "Deletion of the Gria1 gene causes circadian disturbances similar to those reported in schizophrenia." (PMID 34782594, 2021). "In humans, GRIA1 has been linked to the neurological disease schizophrenia, asparaginase hypersensitivity, and migraines." (PMID 30999842, 2019). "For example, GRIA1, the gene encoding the α-amino-3-hydroxy-5-methyl-4-isoxazolepropionic acid (AMPA) receptor subunit GLUA1, has been identified as a putative risk gene for schizophrenia in recent GWAS15,16." (PMID 31000699, 2019). "Genome-wide association studies have suggested a link between schizophrenia and genes associated with synaptic plasticity, including the Gria1 gene which codes for the GluA1 subunit of α-amino-3-hydroxy-5-methyl-4-isoxazolepropionic acid (AMPA) receptor." (PMID 30108203, 2018). "The aberrant learning caused by abnormally high levels of attention to recently experienced stimuli provides a link between Gria1 and abnormal psychological processes implicated in schizophrenia." (PMID 28496171, 2017). "In our dataset, we detected AMPA and NMDA receptor subunits associated with schizophrenia (i.e., GRIA1 and GRIN2A) and with a spectrum of DD/ID, ASD and seizures, often in co-morbidity (GRIA3, GRIN1, GRIN2A, and GRIN2B)." (PMID 28713243, 2017). "Global Gria1 ablation in mice has been used to model certain deficits of synaptic plasticity, dopamine regulation and associated psychological functions related to schizophrenia." (PMID 35288531, 2022). "In line with the glutamatergic hypothesis of schizophrenia, Gria1, the gene that encodes for the GluA1 subunit of the AMPA receptor for glutamate, has genome wide association to schizophrenia." (PMID 33058902, 2021). "Altered levels of glutamate receptor 1, encoded by Gria1, is a risk factor for schizophrenia." (PMID 32582210, 2020). "Gene-targeted mice with deficient AMPA receptor GluA1 subunits (Gria1-/- mice) show robust hyperlocomotion in a novel environment, suggesting them to constitute a model for hyperactivity disorders such as mania, schizophrenia and attention deficit hyperactivity disorder." (PMID 30984001, 2019). "The GluA1 AMPAR subunit (encoded by the Gria1 gene) has been implicated in schizophrenia." (PMID 28496171, 2017). "These include key schizophrenia-associated genes such as FYN proto-oncogene (Fyn) and glutamate ionotropic receptor AMPA type subunit 1 (Gria1)." (PMID 40806558, 2025). "Prior studies have reported elevated Gria1 expression in schizophrenia and neurodevelopmental disorders." (PMID 39628496, 2024). "GluA1 knockout (Gria1−/−) mice provide a model of impaired synaptic plasticity in schizophrenia and exhibit a selective deficit in a form of short-term memory which underlies short-term habituation." (PMID 36460723, 2023). "Gria1, the gene encoding AMPA receptor subunit glutamate A1 (GLUA1), was originally identified as a putative risk gene for schizophrenia." (PMID 36064798, 2022).
schizophrenia (continued). "GluA1 (also known as GluRA or GluR1) is a glutamate receptor subunit of AMPA encoded by the GRIA1 gene, there is genome-wide association between GRIA1 and schizophrenia." (PMID 36561136, 2022). "Decreased GRIA1 mRNA and protein levels have been found in hippocampal tissue from schizophrenia patients in three studies using either in situ hybridisation (ISH) or autoradiography, respectively." (PMID 35288531, 2022). "Decreased GRIA1 expression has been found in the hippocampus of schizophrenia patients in three independent studies." (PMID 36064798, 2022). "The GRIA1 gene encoding the α-amino-3-hydroxy-5-methyl-4-isoxazolepropionic acid (AMPA) receptor subunit GLUA1 has been reported in wide neurological and psychiatric disorders, including schizophrenia." (PMID 35813072, 2022). "Previously, common polymorphic variants from the promoter regions of GRIA1, GRIA3, GRIN1, or GRIN2A were associated with susceptibility to addiction, migraine, or schizophrenia." (PMID 34945722, 2021). "We applied these analyses to simultaneous field recordings from the prefrontal cortex and the ventral and dorsal hippocampus in the schizophrenia-related Gria1-knockout mouse model which displays a robust novelty-induced hyperconnectivity phenotype." (PMID 33557811, 2021). "We have recently shown that the Gria1-KO model, which recapitulates some behavioural deficits relevant to schizophrenia, shows profound and state-dependent aberrations of hippocampal-prefrontal coupling in this task." (PMID 33557811, 2021). "Genetically modified mice that lack Gria1 provide a means of assessing the role of GluA1 in behaviour relevant to the symptoms of schizophrenia." (PMID 33058902, 2021). "Extensive behavioral comparison of Gria1-/- and Gria1+/+ mice suggests a schizophrenia- and depressive-like phenotype." (PMID 30984001, 2019). "Large-scale genome-wide association studies (GWAS) have identified a set of common genetic variants in glutamatergic genes in patients with schizophrenia, including, for instance, GRM3, GRIN2A, GRIA1, SRR, CLCN3, among others." (PMID 31431615, 2019). "Other schizophrenia risk loci with TCF4 binding sites include DRD2, TSNARE1, and GRIA1, all of which are down-regulated in TCF4-depleted cells and MIR137/DPYD." (PMID 29228394, 2018). "Many genes associated with glutamateric neurotransmission have been previously implicated in schizophrenia, including GRM3, GRIN2A, SRR and GRIA1." (PMID 29181591, 2017). "Here, we tested the ability of LY354740 to rescue spatial working memory performance in mice that lack the GluA1 subunit of the AMPA glutamate receptor, encoded by Gria1, a gene recently implicated in schizophrenia by genome‐wide association studies." (PMID 28186680, 2017). "These included schizophrenia candidate genes (GRIA1, RIMS1, DLGAP2, GRIN2A, and NRXN1) and several interaction partners." (PMID 25484875, 2014). "In humans, GRIA1 is involved in memory formation and schizophrenia pathology." (PMID 32867218, 2020). "Mice lacking the putative schizophrenia risk gene GRIA1 (Gria1–/–), which encodes GLUA1, show strongly impaired spatial working memory and elevated selective attention owing to a deficit in stimulus-specific short-term habituation." (PMID 31000699, 2019). "Furthermore, decreased mRNA and protein levels of GRIA1 have also been found in post-mortem hippocampal tissue from schizophrenia patients." (PMID 31000699, 2019). "Furthermore, Gria1−/− mice show behavioural abnormalities that are relevant to schizophrenia suggesting that Gria1 deletion models components of the disorder." (PMID 28785046, 2017). "Finally, a SNP within the NMDAR GRIN2A subunit gene is now genome-wide significant for schizophrenia, as are SNPs at the loci for GRIA1, GRM3 and SRR, all of which impact on NMDAR signalling." (PMID 25315827, 2015).
schizophrenia (continued). "To dissect the role of GluA1 in distinct neuronal circuits, here we examined the behavioural consequences of Gria1 ablation in excitatory cells of either prefrontal cortex or hippocampus in a broad battery of behavioural assays, including back-translational tasks relevant to schizophrenia." (PMID 35288531, 2022). "Furthermore, GRIA1 and GRM3 encoding subunits of the glutamate receptors were shared between schizophrenia and ASD, suggesting that MIA could affect glutamatergic transmission in both of these disorders." (PMID 34859219, 2021). "Therefore, sustained elevation of hippocampal–prefrontal theta coherence may underlie a failure in regulating novelty-related selective attention leading to aberrant salience, and thereby represents a mechanistic link between GRIA1 and schizophrenia." (PMID 31000699, 2019). "The molecules that mostly contributed to discriminate schizophrenia from control were: VGluT2, EAAT2, GAD67, d-Asp/total Asp, d-Ser, PSD-95, GRIA1 and GRM5 whereas the ones that barely contributed to the discrimination were: l-Gln/l-Glu ratio, d-Ser/total Ser, EAAT1, GRIN2A and Gly." (PMID 35217646, 2022). "Multiple evidences showed that GRIA1 and GABRB2 are relevant to Bipolar Disorder and Schizophrenia." (PMID 24901472, 2014).
depression (54 papers, 2009 to 2025). "Nucleotide polymorphisms of Gria1 are associated with serotonin reuptake disorders in patients with depression." (PMID 37089558, 2023). "Evidently, IPA unearthed a substantial number of genes, like Disc169, Syn370, Synpo71, Grin2a, Gria1, Foxo3, and many others which reportedly have been shown to be linked with depressive disorder, bipolar disorder and/or SSDs." (PMID 34362910, 2021). "PPI analysis identified Grin1 and Gria1 as the most central genes in the PPI network; these genes have been previously linked to depression." (PMID 37089558, 2023). "In this module, ADCYAP1R1, PRKACA, MAPK8, MAPK14, GRIA1, and FOS are both targeted genes of CGFC and pathogenic genes of depression; RHOA is a specific targeted gene of CGFC, and most of these genes are related to the pathogenesis or treatment of depression." (PMID 34867413, 2021). "However, the evidence demonstrated that the analyzed anxiety- and depression-related DEGs such as Gria1, Mapk1, Mapk9, and Fkbp5 contributed to anxiety or depression symptoms in rodents." (PMID 33898422, 2021). "In addition, it is well known that the Gria1 gene, ionotropic receptor AMPA type subunit 1, is closely associated with depression and status epilepticus." (PMID 32265642, 2020). "A number of the selected hub genes in our study have been previously reported to be related to FMS or depression, including GRIK1&2, NGF, KCNQ2, GRIA1, TRPV4, IL1A, and GABAA receptors." (PMID 37065490, 2023).
Cognitive impairment (36 papers, 2008 to 2026). Abnormal cognition is characterized by deficits in thinking, reasoning, or remembering. "The dissociation between Arc and Gria1 expression in our study suggests that distinct molecular mechanisms might underpin the observed cognitive deficits and alterations in synaptic plasticity following PSI treatment." (PMID 38963553, 2024).
epilepsy (35 papers, 2015 to 2026). A brain disorder characterized by episodes of abnormally increased neuronal discharge resulting in transient episodes of sensory or motor neurological dysfunction, or psychic dysfunction. "It has been shown that GRIA1 expression is altered in the brains of patients with epilepsy and in animal models of epilepsy." (PMID 39767775, 2024). "Compatible with NEDD4-2 protein level, furthermore, GRIA1 ubiquitination was reduced in epilepsy rats as compared to control animals, which was restored by both AMPAR antagonists in responders." (PMID 34440273, 2021). "These include the AMPAR subunit genes GRIA1, GRIA3, and GRIA4, causing an NDD spectrum including ID, loss of speech, epilepsy, gait abnormalities, and abnormal sleep patterns." (PMID 31300657, 2019). "The increased distribution of GRIA1 on the membrane has been reported in different epilepsy models." (PMID 25915028, 2015). "Thus, we selected GRIA1 and GRIN3A as those of the most upregulated and validated their change in expression in epilepsy by smFISH." (PMID 33028830, 2020). "However, little data are available to describe whether NEDD4-2-mediated GRIA1 ubiquitination is changed, and this alteration is relevant to the generation of refractory seizures to AMPAR antagonists in a chronic epilepsy model." (PMID 34440273, 2021). "Additionally, the mediumblue module (Pvalb subtypes, 173 genes), while not passing the test for associating more strongly with epilepsy than with any sample, included the genes GRIK1, GRIK2, GRIK4, GRM1, GRM7, and GRIA1, suggesting a potential involvement in glutamate receptor subunits." (PMID 33028830, 2020).